MFN1 (mitofusin 1)
Diseases named in the same sentence as MFN1 in open-access papers (continued):
Sharing a sentence is not in itself a finding about the gene and the disease.
tumor (38 papers, 2016 to 2025). "Both of OPA1 and MFN1 were highly expressed in LUAD tumor tissues and OPA1 high expression was associated with poor prognosis." (PMID 36573240, 2022). "As epithelial-to-mesenchymal transition (EMT) is suggested to be closely associated with acquisition of pro-invasive capacities in tumour, we wondered whether MFN1 plays important roles in EMT of HCC cells." (PMID 31819189, 2020). "We propose that Mfn1 silencing can reduce the secretion of these immunosuppressive factors, increasing the percentage of immune cells in the tumor and delaying tumor development." (PMID 38195762, 2024). "Knockdown of OPA1 or MFN1 to inhibit mitochondrial fusion weakened oxygen consumption and cellular ATP production of tumor cells, suppressed cell growth in vitro, and inhibited tumor formation in vivo." (PMID 38812059, 2024). "Both OPA1 and MFN1 exhibit high expression levels in LUAD tumor tissues, with elevated OPA1 expression correlating with poor prognosis." (PMID 38911373, 2024). "Based on this finding, the knockdown of STING or MFN1/2 decreased cell sensitivity to ferroptosis and alleviate imidazole ketone erastin-mediated tumor suppression in a xenograft tumor model." (PMID 36944609, 2023). "MFN1 depletion triggers the epithelial–mesenchymal transition, and the inhibition of MFN1 GTPase activity via FUNDC2 interaction is associated with metabolic reprogramming and tumor growth." (PMID 37627290, 2023). "Overexpression of MFN1 increased mitochondrial size correlating with decreased cell growth, migration, invasion, tumor growth and lung metastasis in vivo." (PMID 35356277, 2022). "Strengthening this data, depletion of MFN1 decreased mitochondrial size correlating with increases in cell growth, migration, invasion, tumor growth and lung metastasis in vivo." (PMID 35356277, 2022). "More importantly, by multiplexed genome editing, knockdown of MFN1 abolished the tumor-suppressive function of shFUNDC2." (PMID 35710796, 2022). "Compared with the control group, IKE-mediated tumor suppression in the STING1KD or MFN1/2KD group was limited." (PMID 34195205, 2021). "In subcutaneous xenograft models, the average volume of MHCC97-H tumour in the MFN1 transfection group was significantly smaller than the control group." (PMID 31819189, 2020). "Analysis of the Oncomine online database, containing five cohorts of HCC patients, revealed that both OPA1 and MFN1 are more highly expressed in HCC tumor tissue compared to liver tissue in the majority of cohorts." (PMID 31947947, 2020). "Upon subcutaneous engraftment in immunodeficient nude mice, we demonstrated that knockdown of OPA1 or MFN1 dramatically inhibited tumor formation and growth of HCC cells in vivo." (PMID 31947947, 2020). "Fusion-related (OPA1, MFN1) as well as fission related (DNM1L) genes were found to be increased in the basal-like subtype when compared to Luminal A tumor samples." (PMID 31231612, 2019). "In animals subjected to chemotherapy with DTIC, Mfn1 silencing also affected tumor growth." (PMID 38195762, 2024). "We reasoned that immunomodulatory proteins secreted by senescent cells would affect tumor progression, and that Mfn1 silencing might mitigate these effects." (PMID 38195762, 2024). "Overall, these results suggest that Mfn1 silencing reduced the secretion of proteins that could affect the immune response towards the tumor." (PMID 38195762, 2024). "Chemotherapy by itself only produced a significant increase in the percentage of macrophages in the tumor, but when the treatment was accompanied by Mfn1 silencing an overall increase in recruitment of immune cells (macrophages, DC, NK cells, and T lymphocytes) was observed." (PMID 38195762, 2024). "Mfn1 silencing per se (shMfn1) delayed tumor growth until day 17 p.t.i.." (PMID 38195762, 2024). "Interestingly, Mfn1 silencing further delayed tumor development in treated animals, and tumor size was significantly smaller in shMfn1 DTIC mice than in all the other conditions." (PMID 38195762, 2024).
tumor (continued). "Also, the proportion of OPA1 and MFN1 in various cells tend to be more distributed in tumor epithelial cells." (PMID 36573240, 2022). "Moreover, inhibition of mitochondrial fusion by knock-down of Opa1 or Mfn1 inhibited cell growth and tumor formation." (PMID 35933403, 2022). "On the basis of metabolic typing, Drp1 or Mfn1/2 proteins might serve as markers for further stratification of tumor chemotherapy resistance." (PMID 34868997, 2021). "On the other hand, downregulation of MFN1 could significantly promote in vivo tumour growth with much larger tumour sizes than control in xenograft models of HepG2 cells." (PMID 31819189, 2020). "MFN1 expression was greatly decreased in tumour tissues compared with para-tumour tissues." (PMID 31819189, 2020). "Furthermore, MFN1 was identified as a tumour-suppressor gene, promoting the mitochondrial fusion to suppress the invasion and metastasis both in vitro and in a xenograft model in vivo." (PMID 31819189, 2020). "In conclusion, Selene could target the mitochondria of tumor cells via the TLR4/TRAF3/MFN1 pathway, induce tumor cell apoptosis, and inhibit inflammatory cytokine secretion in ascites." (PMID 32802180, 2020). "We further detected the expression of MFN1, E-cadherin and Ki67 in xenograft tumours." (PMID 31819189, 2020). "Thus, we explored if Mfn1 silencing would affect immune cell recruitment to the tumor." (PMID 38195762, 2024). "We then explored if Mfn1 silencing could affect tumor development." (PMID 38195762, 2024). "Interestingly, it was found that OPA1 and MFN1 were strongly correlated in tumor epithelial cells." (PMID 36573240, 2022). "Thus, inhibition of Drp1 or overexpression of Mfn1/2 that remodels mitochondrial shape and metabolism could result in decreased proliferation and increased apoptosis of tumor cells." (PMID 34868997, 2021). "Studies have demonstrated that inhibition of MIF expression in tumor cells leads to down-regulation of OPA1 and MFN1 while up-regulating DRP1 expression, resulting in mitochondrial fragmentation." (PMID 38405130, 2024). "In tumor cells treated with PI3K inhibitor (PX-866), mitofusin 1 participates in mitochondrial migration to the cortical cytoskeleton and is required for cell invasion." (PMID 38195762, 2024). "Compared with MFN1 and MFN2, which were slightly elevated in tumor spheres, the transcriptome of OPA1 was dramatically increased in CSCs." (PMID 36809297, 2023). "We identified that OPA1, MFN1, and DNM1L were significantly increased in both NSCLC tumor tissues (P < 0.05)." (PMID 36573240, 2022). "Knockdown of the other two mitochondrial fusion regulatory genes OPA1 or MFN1 attenuates OXPHOS and ATP production of tumor cells." (PMID 35413941, 2022). "If inhibition of MFN1 is a key mechanism of tumor promotion by FUNDC2, overexpression of MFN1 should suppress tumorigenesis similar to FUNDC2 knockdown." (PMID 35710796, 2022). "Taken together, inhibition of MFN1 is playing a critical role downstream of FUNDC2 in regulating mitochondrial fragmentation and respiration in tumor cells." (PMID 35710796, 2022). "Taken together, MFN1 is a critical downstream effector of FUNDC2 in reprogramming glucose and lipid metabolism in tumor cells." (PMID 35710796, 2022). "The interaction role of MFN1 and PINK induced dysregulation of mitophagy process which contributed to glucose-induced pathological epithelial-stromal transformation in tumor cells." (PMID 36157211, 2022). "The knockdown of the fusion regulator genes, OPA1 (Optic atrophy 1) or MFN1 (Mitofusin 1), inhibited the fusion process in HCC cell lines and CCA tumor organoids." (PMID 31947947, 2020). "The expression level of Ki67 was low in OE-MFN1 MHCC97-H xenograft tumours and high in sh-MFN1 HepG2 xenograft tumours." (PMID 31819189, 2020).
tumor (continued). "By genetic knockdown of the key fusion regulators OPA1 or MFN1, we inhibited mitochondrial fusion in HCC cell lines and CCA tumor organoids." (PMID 31947947, 2020). "Consistent with the change of EMT-related protein expression in OE-MFN1 MHCC97-H and sh-MFN1 HepG2, we observed obviously positive correlation between E-cadherin and MFN1 in xenograft tumours from OE-MFN1 MHCC97-H cells and sh-MFN1 HepG2 cells." (PMID 31819189, 2020). "Additionally, silencing of OPA1 or MFN1 decreased mitochondrial fusion in HCC cells and tumor organoids of cholangiocarcinoma, resulting in cell apoptosis in vitro and tumor growth after tumor cell engraftment in nude mice." (PMID 38299199, 2024). "In agreement, tumors lacking mitofusin 1 responded better to treatment with the methylating agent dacarbazine, tumor size was reduced and a higher immune cell infiltration was detected in the tumor." (PMID 38195762, 2024). "Lack of mitofusin 1 reduced galectin-9 protein levels and strongly influenced immune cell recruitment and tumor development, highlighting the potential of mitochondria as a target in cancer treatment." (PMID 38195762, 2024). "We observed that Mfn1 silencing resulted in a smaller tumor volume even in the absence of treatment (day 12 p.t.i.)." (PMID 38195762, 2024). "Reduction of MFN1 induces mitochondrial fission in HCC and promotes tumor growth." (PMID 36831455, 2023). "Studies have found that key molecules involved in the regulation of mitochondrial fission and fusion, such as Drp1, MFN1, and MFN2, are abnormally expressed in a variety of tumor tissues, and may be closely related to tumor progression." (PMID 36034426, 2022). "Moreover, our results indicate that the fasting induction of FOXO3a, ACC, and MuRF‐1 requires AMPK, as does the fasting regulation of mitochondrial quality control proteins MFN‐1 and DRP‐1 in tumor‐bearing mice." (PMID 34270178, 2021). "The differences in tumor volume between animals bearing tumors with and without mitofusin 1 were more prominent in intradermal than subcutaneous tumors, maybe because in this site of implantation tumors are more susceptible to the immune response." (PMID 38195762, 2024). "At day 10 post-tumor inoculation (p.t.i.), when tumors became palpable, we injected conditioned media from cells in different conditions (non-senescent and senescent cells with or without out Mfn1 silencing)." (PMID 38195762, 2024). "Thus, by inhibiting MFN1, FUNDC2 could promote tumor growth by metabolic reprogramming following dysregulated mitochondrial dynamics." (PMID 35710796, 2022). "Additionally, knockout of MFN1 in endothelial cells did not affect melanoma primary tumor growth in vivo." (PMID 35356277, 2022). "However, we did not detect differences in the mRNA levels of these factors between tumors with and without mitofusin 1, maybe because other immune cells present in the tumor can also express Ccl5 and Lgals9." (PMID 38195762, 2024). "The activity of caspase-3 (an apoptosis marker) and the mRNA expression of STING1, MFN1, and MFN2 in tumor extracts was not changed by IKE." (PMID 34195205, 2021). "However, there is no previous study investigating the role of MFN1 and TOMM22 in the progression of CRC, we are the first study revealing the tumor suppressor role of these two genes, Especially TOMM22 which was overexpressed in the tumor samples." (PMID 36333388, 2022).
infection (13 papers, 2010 to 2024). The state of being infected such as from the introduction of a foreign agent such as serum, vaccine, antigenic substance or organism. "We found that during early infection time points, hRSV infection promotes mitochondrial fusion associated with mitofusins (Mfn1) mRNA downregulation." (PMID 37515204, 2023). "On the other hand, in other viruses, such as dengue virus and measles virus, the relationship between hyperfusion and Mfn1 expression during the infection processes has been directly studied." (PMID 37515204, 2023). "Similar to these reports, release of mtDNA during either WT or iF17 infection was suppressed by MFN1 depletion." (PMID 38036506, 2023). "Generally, the individual infection ratio of Dnm1l or Mfn1 was around 65% in both AAC alone and AAV-treated mice." (PMID 36276651, 2022). "We found that SARS-CoV-2 infection does not cause a reduction in MFN1/2 expression during the early stage of infection." (PMID 38734691, 2024). "Our study indicated an increased colocalization of MAVS with Mfn1/2 during infection only in cells exhibiting an unaltered or elongated mitochondrial network, which could imply enhanced interactions between these proteins." (PMID 39338909, 2024). "Infection with hRSV ON1 resulted in downregulation of the Mfn1, VDAC2, and PINK1 mRNAs." (PMID 37515204, 2023). "Furthermore, induction of ISGs in response iF17 infection was significantly reduced by depletion of MFN1." (PMID 38036506, 2023). "Interestingly, MFN1 depletion only had significant impacts on glycolysis in infected cells in the absence of its inhibitor, F17, in agreement with the idea that infection-induced hyperfusion is an important driver of increases in glycolysis as part of the overall host response." (PMID 38036506, 2023). "During infection with human immunodeficiency type 1 (HIV-1), MFN1 and MFN2 are upregulated in macrophages in a TREM1-dependent manner." (PMID 34482801, 2021). "We foundthat there was a significant increase of Mfn1 and Mfn2 levels in theinfected lung tissues compared to tissues without the infection bySARS-CoV-2." (PMID 38386664, 2024). "suggest that the downregulation of VDAC2, Mfn1, and PINK might be an antiviral response that limits the progression of the infection and therefore at these time points most mitochondria have normal morphology." (PMID 37515204, 2023). "Mitochondrial morphology plays an important role on the MAVS-mediated antiviral response originating from this organelle: upon infection, mitochondrial MAVS activation allows the induction of the mitochondrial fusion protein mitofusin-1 (MFN1), leading to the organelle’s fusion." (PMID 35445031, 2022). "The levels of mfn-1 and mfn-2 were significantly decreased by ~2-fold in cholesterol treated infected cells, whereas mfn-2, but not mfn-1, was downregulated by ~2-fold during infection in untreated cells." (PMID 29067283, 2017). "However, it remains unclear why MFN2 but not MFN1 is required for immunometabolic remodeling in macrophages during infection." (PMID 34482801, 2021). "After infection of PS2 D439A mutant SH-SY5Y cells with Ad-Miro2 adenovirus, the increased expression of Miro2 resulted in increases in the Mfn1 and Mfn2 levels but not the Drp1 level compared to those in the Ad-NC group." (PMID 38159198, 2024).
heart disease (8 papers, 2012 to 2025). "Mitochondrial morphological changes are often seen in human heart diseases, and knockout mice of mitochondrial fusion factor Mfn1/2 cause cardiac abnormalities, suggesting that maintenance of mitochondrial morphology (dynamics) plays an essential role in maintaining cardiac function." (PMID 35789860, 2022). "Downregulation or post-translational modification of these fusion proteins have been confirmed as related to a variety of heart diseases, however, the specific mechanisms through which MFN1, MFN2, and OPA1 function in cardiomyocytes require further research." (PMID 34660720, 2021). "To date, many studies have confirmed that the fusion and fission dynamins of cardiac mitochondria, in particular the GTPase dependent dynamins (DRP1, MFN1, MFN2, OPA1) are associated with the occurrence and development of various heart diseases." (PMID 34660720, 2021). "On the other hand, if our idea is correct that the dominant inhibitory effect of Mfn2 400Q relates to its disruption of both homotypic (i.e. Mfn2-Mfn2) and heterotypic (i.e. Mfn1-Mfn2) mitofusin interactions, then its pathological potential should be equally great in mammalian heart disease." (PMID 22957060, 2012). "We posit that precise modulation of the activities of Drp1, Mfn1/2, and OPA1 presents significant potential for the treatment of cardiac diseases." (PMID 41000071, 2025). "As mitochondrial fission and fusion are primarily regulated by mitochondrial dynamins in a GTPase-dependent manner, GTPase-dependent mitochondrial fusion (MFN1, MFN2, and OPA1) and fission (DRP1) proteins, which are abundant in the adult heart, can also be regulated in heart diseases." (PMID 34660720, 2021).
metabolic disorders (3 papers, 2019 to 2025). "For instance, compounds such as mdivi-1, P110, dynasore, and S3, which interfere with Drp1 function or inhibit MFN1/2, effectively reduce excessive mitochondrial fission, highlighting their potential therapeutic value in treating metabolic disorders." (PMID 40804395, 2025). "Altogether, the effects of MFN2 depletion are consistent with a greater pathophysiological relevance of MFN2 than of MFN1, exemplified by the involvement of MFN2 in metabolic disorders and neurodegeneration." (PMID 39929801, 2025).
neurodegenerative disease (3 papers, 2015 to 2025). A disorder of the central nervous system characterized by gradual and progressive loss of neural tissue and neurologic function. "Defects in MFN2- and MFN1- mediated mitochondrial fusion have been associated with various neurodegenerative diseases, including PD." (PMID 41035822, 2025). "In the process of mitochondrial fusion both Mitofusin-1 and -2 have been reported to contribute, and although they share a common function in this process; deficiency in Mitofusion-2, but not Mitofusin-1, has been linked to neurodegenerative diseases." (PMID 29267236, 2017).
peripheral neuropathy (3 papers, 2022 to 2023). A disorder affecting the peripheral nervous system. "Alternatively, impediment of mitochondrial fusion (ensured by OPA-1 and Mfn1/2) is associated peripheral neuropathy." (PMID 35677375, 2022). "Interestingly, no known MFN1 mutations cause peripheral neuropathy, which may be due to the relatively low expression of MFN1 in neurons." (PMID 37508383, 2023).
inflammatory myopathy (2 papers, 2023 to 2025). "Although MFN1 and OPA1 deficiency can cause inflammatory myopathy in mouse muscle KO models, the role of mtDNA-mediated inflammation in MFN2 pathology has not been fully explored." (PMID 40175090, 2025). "Taken together, skeletal muscle Mfn1 ablation triggers muscle inflammation and muscle atrophy, thereby suggesting that the SkM-Mfn1KO mouse is a model of inflammatory myopathy." (PMID 36609505, 2023). "Notably, a recent study showed that inducible muscle-specific loss of MFN1 causes mtDNA release via early endosomes, leading to activation of TLR9/NF-κB inflammation and myopathy." (PMID 40175090, 2025). "However, more recent work linking MFN1 and OPA1 muscle deficiency to inflammation-mediated myopathy showed that blocking the inflammation was protective in these models, arguing for a key role of inflammation in the muscle pathology caused by impaired mitochondrial fusion." (PMID 40175090, 2025).
renal disease (1 paper, 2021). "Studies have shown that the expression of mitochondrial dynamic proteins, Drp1 and Fis1, are upregulated, while Mfn1 expression is down-regulated in early-stage renal disease." (PMID 33902473, 2021). "The results indicate that abnormal mitochondrial dynamics may participate in CIH-induced kidney disease progression, and the expression of p66Shc, Fis1 and Mfn1 is closely related to disease severity." (PMID 33902473, 2021).
reproductive diseases (1 paper, 2022). "However, the role of Mfn2, especially the upstream and downstream molecular mechanisms mediating the effects of Mfn2 on reproductive diseases has yet to be dissected; in particular, studies that specifically target the reproductive disorders caused by Mfn1 have yet to emerge." (PMID 35725948, 2022).